E2F4 (E2F transcription factor 4)
Diseases named in the same sentence as E2F4 in open-access papers (continued):
Sharing a sentence is not in itself a finding about the gene and the disease.
pancreatic cancer (7 papers, 2017 to 2025). "The transcription factors NFYC, TFDP3, POLE3 and E2F4 are closely linked to hub genes in pancreatic cancer." (PMID 32587798, 2020). "The interaction between recombinant OFD1 and E2F4 was further validated by endogenous immunoprecipitation (IP) in three pancreatic cancer cell lines and an in vitro pulldown assay (, j)." (PMID 40764600, 2025). "In conclusion, we reported the nucleolus localization and pro-proliferative effect of NOP14 by simultaneously activating downstream miR17-5p and E2F4 signaling in human pancreatic cancer." (PMID 37506248, 2023). "We observed that oncogenes intersecting with the RB pathway and known as cell-autonomous inducers of G1/S transition (e.g. E2F1, E2F4), supported proliferation, chemoresistance and cell migration of pancreatic cancer cells via inducing the secretion of canonical WNT signalling." (PMID 38678032, 2024). "Next, we explored correlation between E2F4, CCNE1, CCND1 and NOP14 in pancreatic cancer tissue in TCGA database." (PMID 37506248, 2023). "Given that OFD1 is predominantly localized in the cytoplasm of pancreatic cancer cells, we hypothesized that OFD1 regulates E2F4 translocation through interaction in the cytoplasm." (PMID 40764600, 2025).
gastric cancer (6 papers, 2015 to 2025). A primary or metastatic malignant neoplasm involving the stomach. "Further investigation revealed that POLQ regulated DHODH expression via the transcription factors E2F4, thereby regulating ferroptosis resistance and stemness of gastric cancer cells." (PMID 38575587, 2024). "Briefly, our data indicate that E2F4 significantly influences the proliferation, migration, and invasion of gastric cancer cells." (PMID 39309429, 2024). "The results demonstrated that E2F1, E2F2 and E2F4 were overregulated in the gastric cancer samples compared with normal samples." (PMID 25646628, 2015). "It has been reported that E2F4 binds directly with USP2 (ubiquitin specific peptidase 2) in gastric cancer cells, while USP2 could bind with SKP2 and USP2-stabilized SKP2 did not destabilize its substrate P21." (PMID 38980592, 2025). "Indeed, we found that target genes regulated by E2F1 and E2F4 appeared quantities of differential expression in gastric cancer, which indicates that E2F1 and E2F4 are very likely to occupy an important share in growth of gastric cancer." (PMID 25646628, 2015).
liver cancer (6 papers, 2017 to 2023). An epithelial or non-epithelial malignant neoplasm that arises from the liver. "In support of our results, studies have demonstrated that E2F4 function as crucial regulator in liver cancer." (PMID 33613768, 2021). "Studies have shown that E2F mRNA expression levels are related to different cancer stages and pathological grades of HCC patients, and E2F4 protein is highly expressed in advanced liver cancer." (PMID 34335934, 2021). "E2F4 is a downstream target of ZBTB7, which was associated to the expression of cell cycle-associated genes in liver cancer cells." (PMID 28347313, 2017). "We found that E2F4 could be identified as a regulator of hub genes in liver cancer." (PMID 33613768, 2021). "Remarkably, a similar enrichment for YY1, NRF1, E2F4, and FOXP3 TFs was also identified by GO-Elite in both the livers of miR-122 KO animals (GSE31453) and in the mouse model for liver cancer (GSE27713)." (PMID 37627157, 2023).
bladder cancer (5 papers, 2014 to 2022). "Moreover, lncRNA GAS5 was reported to suppress enhancer of zeste homolog 2 (EZH2) transcription via recruiting E2F4 to EZH2 promoter to induce bladder cancer cell apoptosis." (PMID 32308561, 2020). "More specifically, GAS5 has the potential to inhibit EZH2 transcription by directly interacting with E2F transcription factor 4 (E2F4) and recruiting E2F4 to the promoter of EZH2 in bladder cancer cells." (PMID 34781960, 2021). "Most notably, upregulated lncRNA GAS5 has been demonstrated to inhibit the transcription of EZH2 via recruitment of E2F4 to EZH2 promoter and induced cell apoptosis of bladder cancer." (PMID 32308561, 2020). "E2F4 activity level significantly correlates with survival time in bladder cancer (P = 0.01) and glioblastoma (P = 0.007), but not in NSCLC, AML or Burkitt’s lymphoma (P >0.05)." (PMID 25440089, 2014).
Burkitt lymphoma (5 papers, 2014 to 2021). A rare form of malignant mature B-cell non-Hodgkin lymphoma. "E2F4 takes part in the transcription regulation of multiple key genes in the Burkitt lymphoma tumorigenesis." (PMID 34252883, 2021). "Of note, EGR2 mutations have been detected in clinically aggressive CLL subgroups while E2F4, a key regulator of the cell cycle, has been reported deregulated in both Burkitt lymphoma and diffuse large B cell lymphoma." (PMID 31791414, 2019). "Furthermore, up‐regulated E2F4 led to the suppression of cell proliferation and tumorigenesis of Burkitt lymphoma." (PMID 32314545, 2020). "E2F4 has been reported to be downregulated in Burkitt lymphoma and upregulated in DLBCL38." (PMID 25891015, 2015).
glioblastoma (5 papers, 2007 to 2023). The most malignant astrocytic tumor (WHO grade IV). "Consistent with a global role in maintaining quiescence, E2F4 has been shown to bind to and regulate a set of proliferation and cell cycle related targets in a number of ex vivo human cell lines, including glioblastoma, fibroblast, and osteoblasts." (PMID 17957245, 2007). "It has been reported that E2F4 expression is upregulated in glioblastoma cells." (PMID 37349788, 2023). "Furthermore, the high overlap of E2F4 bound genes in the diverse human tissues we characterized indicates that the regulatory mechanisms used by the DREAM complex to control entry into cell cycle in human glioblastoma cells are likely employed in all human tissues." (PMID 17957245, 2007).
melanoma (5 papers, 2018 to 2024). A malignant, usually aggressive tumor composed of atypical, neoplastic melanocytes. "Further studies will be necessary to determine the respective contribution of E2F1 and E2F4 in the effects of HLM006474 in melanoma cells." (PMID 29743521, 2018). "Dysregulated transcriptional activity of E2F family within the melanoma cells drives ongoing proliferation, with E3F2 and E2F4 being especially prominent in actively dividing melanoma cells." (PMID 38674007, 2024). "As blocking E2F4 also inhibited melanoma cell viability, it is not excluded that the effects of HLM006474 could also be mediated by E2F4 inhibition." (PMID 29743521, 2018).
skin tumors (5 papers, 2016 to 2025). "For example, E2F4 induced proliferation and promoted the development of skin tumors in a keratin 5 promoter-driven E2F4 transgenic mice." (PMID 34136392, 2021). "Overexpression of E2F4 in the epidermis, particularly in conjunction with DP1, results in skin tumors." (PMID 40508152, 2025). "High levels of E2F4 are also present in a mouse model of skin cancer, and overexpression of E2F4 in epidermis, particularly in conjunction with DP1, results in skin tumors." (PMID 27753528, 2016). "The two proteins also differ in their oncogenic potential: Only E2F4 transgenic but not E2F1 transgenic mice developed skin tumors." (PMID 26751588, 2016).
head and neck squamous cell carcinoma (4 papers, 2020 to 2025). A squamous cell carcinoma that arises from any of the following anatomic sites: lip and oral cavity, nasal cavity, paranasal sinuses, pharynx, larynx, and salivary glands. "In head and neck squamous cell carcinoma, high E2F4 expression is linked to poor prognosis, with IHC analysis showing elevated levels of E2F445." (PMID 39309429, 2024).
leukemia (4 papers, 2014 to 2025). A malignant (clonal) hematologic disorder, involving hematopoietic stem cells and characterized by the presence of primitive or atypical myeloid or lymphoid cells in the bone marrow and the blood. "Proximal labeling results showed that SETD1A and E2F4 closely localized to the chromatin in leukemia; however, their transcriptional activation functions have not been determined." (PMID 40846851, 2025). "To confirm the function of E2F4 in leukaemia cells, we used lentiviral transfection to silence E2F4 expression in NB4 and THP‐1 cells." (PMID 31943751, 2020). "The flow cytometry results showed that the proportion of G0/G1 population in the E2F4‐depleted leukaemia cells was higher than that in the NC group cells, indicating that E2F4 knockdown blocked cell cycle progression." (PMID 31943751, 2020). "Next, we used flow cytometry to investigate whether E2F4 knockdown induced leukaemia cell cycle arrest." (PMID 31943751, 2020). "We used a series of experimental methods to detect whether E2F4 could affect leukaemia cell differentiation." (PMID 31943751, 2020). "In addition, the E2F4 expression was significantly elevated in a number of leukaemia cell lines compared with that in the normal human monocytes." (PMID 31943751, 2020). "Taken together, these data suggest that silencing E2F4 may contribute to leukaemia differentiation." (PMID 31943751, 2020). "In summary, E2F4 may become a target protein for leukaemia treatment." (PMID 31943751, 2020). "Some top ranked regions suggested co-binding of E2F4 with the core transcriptional machinery such as TBP and Pol2 in lymphoma (CH12 tracks) and leukemia (MEL tracks)." (PMID 27098038, 2016). "The Co‐IP results showed significant binding of E2F4 and EZH2 in leukaemia cells and AML patients." (PMID 31943751, 2020).
osteosarcoma (4 papers, 2007 to 2025). A usually aggressive malignant bone-forming mesenchymal neoplasm, predominantly affecting adolescents and young adults. "Furthermore, although prior studies have shown that E2F regulation of cIAPs and E2F1 directly promotes MAP3K14 gene expression in osteosarcoma cells, we report for the first time that the E2F transcription factors E2F4 and E2F5 play a role in regulating NIK transcription and expression." (PMID 36945490, 2023).
acute myeloid leukemia (3 papers, 2014 to 2023). Acute myeloid leukemia (AML) is a group of neoplasms arising from precursor cells committed to the myeloid cell-line differentiation. "E2F4 represses the MAPK signaling pathway by binding with EZH2, thereby inhibiting the progression of acute myeloid leukemia." (PMID 37349788, 2023).
breast tumors (3 papers, 2017 to 2022). "The relevance of iRASMDA with cell proliferation was further confirmed by its high positive correlation with the E2F4 score (Pearson Coefficient R = 0.93), which is calculated based on an E2F4 gene signature that serves as an accurate indicator of cell proliferation in breast tumor cells." (PMID 29100329, 2017). "For example, events in CYB561 and CEACAM1 are enriched in HER2+, and E2F4, AP2A2, MGAT4B, and DUXAP9 events are enriched in basal-like breast tumors." (PMID 35044822, 2022).
endometrial cancer (3 papers, 2018 to 2020). Primary or metastatic malignant neoplasm involving the endometrium (mucous membrane that lines the endometrial cavity). "The expression of E2F1/2/3/7/8 was significantly upregulated in endometrial cancer tissues, converse to E2F4, which was downregulated." (PMID 33329696, 2020). "Besides, we verify that ZBTB7A can repress the transcription of E2F4, which may be responsible for function of ZBTB7A in endometrial cancer." (PMID 33292231, 2020).
esophageal squamous cell carcinoma (3 papers, 2020 to 2025). Esophageal squamous cell carcinoma (ESCC) is a type of esophageal carcinoma (EC) that can affect any part of the esophagus, but is usually located in the upper or middle third. "The correlation between SNRPB2 and E2F4 protein expression in esophageal squamous cell carcinoma." (PMID 40612943, 2025). "Previous studies showed that in esophageal squamous cell carcinoma, LINC00337 could recruit E2F4 to upregulate TPX2 transcription, form LINC00337/E2F4/TPX2 axis." (PMID 33292231, 2020).
lung adenocarcinoma (3 papers, 2009 to 2024). A carcinoma that arises from the lung and is characterized by the presence of malignant glandular epithelial cells. "We found that the expression levels of E2F1/2/3/5/6/7/8 were higher in lung adenocarcinoma and squamous cell lung carcinoma tissues than in lung tissues, whereas the expression level of E2F4 was lower in the former than in the latter." (PMID 29754146, 2018). "The results indicated that the expression levels of E2F1, E2F2, E2F3, E2F5, E2F6, E2F7, and E2F8 were higher in lung adenocarcinoma and squamous cell lung carcinoma tissues than in lung tissues, whereas and the expression level of E2F4 was lower in the former than in the latter." (PMID 29754146, 2018). "Complex effects on rRNA transcription, both positive and negative, have been ascribed to E2F1, E2F4, and E2F6, when studied in transfected human lung adenocarcinoma H358 cells." (PMID 19838300, 2009).
lymphoma (3 papers, 2009 to 2022). A malignant (clonal) proliferation of B- lymphocytes or T- lymphocytes which involves the lymph nodes, bone marrow and/or extranodal sites. "Finally, a deficiency in E2F4 also had a dramatic effect on Myc-induced lymphoma development." (PMID 19749980, 2009). "The largely late-onset lymphomas from E2f4-null mice also demonstrated disruptions in this pathway." (PMID 19749980, 2009). "Lymphoma onset may be modestly delayed in E2f4+/− mice (p = 0.0465)." (PMID 19749980, 2009). "The work we present here provides clear evidence for an interaction between Myc and two E2Fs as seen by the effect on timing of tumor onset and the different characteristics of the lymphomas that arise in the absence of E2F2 or E2F4." (PMID 19749980, 2009).
Obesity (3 papers, 2022 to 2023). Accumulation of substantial excess body fat. "Therefore, E2F4 seems to be linked to multiple pathways involved in obesity and energy metabolism, and this property may underscore the capacity of E2F4DN to reverse weight loss in 5xFAD mice without leading to obesity in WT mice." (PMID 35254651, 2022). "E2F4 and CLOCK are associated with prognosis in patients with diabetes mellitus and obesity." (PMID 36837510, 2023).
Alzheimer disease (2 papers, 2021 to 2022). A progressive, neurodegenerative disease characterized by loss of function and death of nerve cells in several areas of the brain leading to loss of cognitive function such as memory and language. "Interestingly, E2F4 malfunction has been linked to cognitive impairment, as well as to the etiopathology of neurodegenerative diseases, such as Alzheimer’s disease (AD)." (PMID 36292945, 2022). "This mutant form, or E2F4, prevents cell cycle re-entry in developing neurons and is able to prevent Alzheimer’s disease (AD)-deleterious processes in 5xFAD mice, a murine model of this disease." (PMID 36292945, 2022).
anemia (2 papers, 2022 to 2023). A reduction in the number of red blood cells, the amount of hemoglobin, and/or the volume of packed red blood cells. "Particularly, the Baso stage arrest of Z-DON-treated cells observed here phenocopies the macrocytic anemia associated with E2F4 knockout mice." (PMID 37169024, 2023). "E2F4 knockout mice showed a broad range of phenotypes, including aberrant hematopoietic lineage development, leading to anemia." (PMID 35505416, 2022).
B-cell Lymphoma (2 papers, 2016 to 2019). "This is a bigWig file for E2F4 ChIP-seq in B-cell Lymphoma (CH12)." (PMID 27098038, 2016). "The E2F2 and E2F4 factors bind to the E2 recognition motif and are involved in cell cycle processes, DNA damage response and regulate TERT transcription in human B-cell lymphoma." (PMID 31888467, 2019).
Cognitive impairment (2 papers, 2021 to 2022). Abnormal cognition is characterized by deficits in thinking, reasoning, or remembering. "E2F4 has been related to cognitive impairment and the pathogenesis of AD, as well as to other neurological diseases, including Parkinson ́s disease/mild cognitive impairment." (PMID 36292945, 2022). "Therefore, E2F4 is a potential therapeutic target for diseases with cognitive impairment, such as AD." (PMID 36292945, 2022). "Whether E2F4 might be useful as a biomarker of early detection of cognitive impairment and monitoring of the course of the disease should be addressed by increasing the number of patients." (PMID 33767277, 2021).
COVID-19 (2 papers, 2022 to 2023). A disease caused by infection with severe acute respiratory syndrome coronavirus 2. "Furthermore, our research indicates that transcription factors FOXC1, GATA2, YY1, NR2C2, and E2F4 were overexpressed in common DEGs of psychiatric disorders and COVID-19." (PMID 35185890, 2022).